WASH8P (WAS protein family homolog 8, pseudogene)
Gene: Transcribed unprocessed pseudogene on chromosome 12 (14,522 to 32,015, reverse strand). Ensembl gene ENSG00000226210.
Diseases named in the same sentence as WASH8P in open-access papers:
WASH8P is named in the same sentence as 1 disease in open-access papers, as found by Europe PMC text mining. Sharing a sentence is not in itself a finding about the gene and the disease. The quoted sentences say what the papers report.
cancer (1 paper, 2021). A tumor composed of atypical neoplastic, often pleomorphic cells that invade other tissues. "Other cancer-related genes are ADAMTS17, LINC01748, LPAL2, SRP14-AS1 and WASH8P." (PMID 33672117, 2021).